Y_RNA (Y RNA )
Gene: Miscellaneous RNA gene on chromosome 2 (82,307,067 to 82,307,168, reverse strand). Ensembl gene ENSG00000201311.
Homologues: Orthologues: chimpanzee Y_RNA (98% identical), macaque Y_RNA (91% identical), dog Y_RNA (82% identical). Paralogues in human: Y_RNA (86% identical), Y_RNA (85% identical), RNY3 (84% identical), Y_RNA (84% identical), RNY3P1 (83% identical), Y_RNA (83% identical), Y_RNA (82% identical), RNY3P14 (81% identical), Y_RNA (81% identical), RNY3P5 (80% identical), Y_RNA (80% identical), RNY3P11 (79% identical), and 93 more.